ARID1B (AT-rich interaction domain 1B)
Diseases named in the same sentence as ARID1B in open-access papers (continued):
Sharing a sentence is not in itself a finding about the gene and the disease.
intellectual disability syndromes (2 papers, 2021 to 2025). "However, the high sequence similarity between ARID1B and ARID1A and the association of ARID1B loss with intellectual disability syndromes pose challenges for the development of small‐molecule inhibitors that are selectively ARID1B‐specific and can be precisely delivered to affected tissues." (PMID 40671262, 2025).
lymphoma (2 papers, 2020 to 2025). A malignant (clonal) proliferation of B- lymphocytes or T- lymphocytes which involves the lymph nodes, bone marrow and/or extranodal sites. "ARID1B, a subunit of the SWI/SNF chromatin complex, is also frequently mutated in aggressive lymphomas, including hepatosplenic T cell lymphoma and DLBCL." (PMID 32349779, 2020).
neurofibroma (2 papers, 2021 to 2022). An intraneural or extraneural neoplasm arising from nerve tissues and neural sheaths. "Molecularly, JAK activates STAT signaling, which transcriptionally represses the epigenetic regulator ARID1B, leading ultimately to neurofibroma initiation and maintenance." (PMID 35741605, 2022).
Strabismus (2 papers, 2021 to 2023). A misalignment of the eyes so that the visual axes deviate from bifoveal fixation. "As a result, we found three genes (ARID1B, ARNT2, COL4A1) intersected with the HPO strabismus gene list." (PMID 33435129, 2021).
Aleutian disease (1 paper, 2024). "From this, we identified several candidate genes contributing to the growth and feed efficiency (ARID1B, APPL1, TOX, and GPC5), reproduction (GRM1, RNASE10, WNT3, WNT3A, and WNT9B), pelt quality (MYO10, and LIMS1), and Aleutian disease tests (IFNGR2, APEX1, UBE3A, and STX11)." (PMID 38167844, 2024).
anaemia (1 paper, 2024). "This seems to suggest that if the increased expression of ARID1B had an ameliorating effect on space anaemia while in-flight in this case, this was likely achieved through pathways other than GATA1-mediated differentiation and erythroid maturation." (PMID 38862545, 2024). "Thus, the down-regulation of ARID1B could be interpreted as a response mechanism for space anaemia, with its reduced expression possibly opposing the reduced red blood cell counts in astronauts in flight." (PMID 38862545, 2024).
atherosclerosis (1 paper, 2026). A disease characterized by the build-up of fatty material and calcium deposition in the arterial wall resulting in partial or complete occlusion of the arterial lumen. "ARID1B was identified as a gene discriminating cuproptosis status in atherosclerosis pathology, with significantly reduced expression in the disease group." (PMID 42227004, 2026).
atypical teratoid rhabdoid tumor (1 paper, 2023). Atypical teratoid rhabdoid tumor (ATRT) is a highly malignant central nervous system (CNS) rhabdoid tumor (RT) found almost exclusively in children. "However, ARID1B loss has not yet been reported in pediatric and young adult undifferentiated malignancies, such as SCCOHT and SMARCA4-deficient uterine sarcoma (SDUS), or malignant rhabdoid tumors of the kidney (MRT), and atypical teratoid rhabdoid tumor (ATRT)." (PMID 37686505, 2023).
B-cell lymphomas (1 paper, 2023). "Mutational profiling using a custom panel of 168 genes associated with aggressive B-cell lymphomas confirmed mutations in ACTB, ARID1B, DUSP2, DTX1, HLA-B, PTEN, and TNFRSF14." (PMID 36975733, 2023).
brachydactyly (1 paper, 2022). A disease characterized by the presence of brachydactyly, including syndromic and non-syndromic forms. "Our patient can be described as a case with mild brachydactyly with a novel ARID1B variant." (PMID 35879281, 2022).
brain tumors (1 paper, 2018). "Genetic defects in ARID1A, ARID1B, and CHEK2 have been reported in brain tumors." (PMID 29610389, 2018).
Chiari malformation type I (1 paper, 2018). Arnold-Chiari malformation type I is a central nervous system malformation characterized by caudal displacement of the cerebellar tonsils exceeding 5mm below the foramen magnum with or without syringomyelia. "Brain imaging identified a Chiari malformation Type I. Subsequent exome sequencing identified two frame-shift mutations in ARID1B in close proximity (c.5151del and c.5153del), both resulting in a premature stop codon in the 48th amino acid downstream of the mutation (p.Lys1718Argfs*48)." (PMID 30459321, 2018).
chordoma (1 paper, 2025). Chordomas are rare malignant tumors arising from embryonic remnants of the notochord in axial skeleton. "Pediatric chordoma is characterized by a higher prevalence of germline ARID1B indels (22% vs. 5% in adults) and more frequent loss of INI1 (SMARCB1), especially in poorly differentiated cases." (PMID 39941902, 2025). "These mutations affect various subunits of the SWI/SNF chromatin remodeling complex, with ARID1A being the most frequently mutated gene, followed by SMARCA4, ARID1B, ARID2, PBRM1, and SMARCB1, mutations we have found to be common in adult chordoma." (PMID 39941902, 2025).
choriocarcinoma (1 paper, 2020). An aggressive malignant tumor arising from trophoblastic cells. "ARID1A expression was detected in type II GCT tissues (GCNIS, seminomas, ECs, teratomas) and cell lines (TCam-2 (seminoma), 2102EP, NCCIT (ECs), JAR (choriocarcinoma)), while ARID1B expression was expressed considerably weaker." (PMID 32272809, 2020).
colorectal tumors (1 paper, 2025). "This compensatory ARID1B upregulation is commonly seen in poorly differentiated, aggressive cancers, such as colorectal tumors, where ARID1A expression is low and ARID1B is elevated." (PMID 40806597, 2025).
corpus callosum agenesis (1 paper, 2021). "The AT-rich interactive domain-containing protein 1B (ARID1B) gene has also been consistently associated with ASD and syndromic and non-syndromic ID, and corpus callosum agenesis and is similarly considered a high confidence gene for ASD with over 100 rare single gene variants." (PMID 34858139, 2021).
diffuse large B-cell lymphoma (1 paper, 2024). "Among BAF subunits, ARID1A, ARID1B, and SMARCA4 are each mutated in ~10% of Diffuse Large B-Cell Lymphomas (DLBCL), which are thought to originate from malignant transformation of germinal center B cells." (PMID 38313292, 2024).
fibroepithelial polyp (1 paper, 2025). A polypoid lesion composed of fibrous tissue and epithelium. "The ARID1B: p.T2124M variant was present in all, SCC and normal tissue, as it was in the fibroepithelial polyp, likely representing a germline variant." (PMID 40936011, 2025). "The other mutations found in our case (DNMT3A, C8B, TET2, SDHA, ARID1B, NOTCH1, OR5L1, and KDM6A) do not have a known association with the formation of fibroepithelial polyps." (PMID 40936011, 2025).
glioma (1 paper, 2021). A benign or malignant brain and spinal cord tumor that arises from glial cells (astrocytes, oligodendrocytes, ependymal cells). "We next repeated this process for each grade of glioma and found that these enhancers regulated a number of cancer-related genes, such as ARID1B 39, EGFR, MDM2 40, PRGFRA, and MYC." (PMID 33537074, 2021). "Particularly, MYC, CCND2, and ARID1B were regulated by more than six enhancers in gliomas." (PMID 33537074, 2021).
hemangioblastoma (1 paper, 2014). "Of note, two missense mutations in ARID1B were identified in two separate hemangioblastomas, at amino acid positions 647 and 651, with predicted allelic fractions of 2-6% and cancer cell fraction of 8-32%, suggesting subclonality." (PMID 25589003, 2014). "The validation cohort consisted of 22 sporadic hemangioblastomas, for which the exons of 560 genes (including VHL and ARID1B) and 39 translocations previously implicated in cancer were sequenced at an average depth of 182x." (PMID 25589003, 2014).
Hip dysplasia (1 paper, 2019). The presence of developmental dysplasia of the hip. "However, the dogs with hip dysplasia do not exhibit similar multisystemic symptoms as the CSS patients with causative ARID1B mutations." (PMID 31323019, 2019).
Lissencephaly 3 (1 paper, 2025). "The ARID1B gene, associated with Coffin-Siris syndrome 1 (MIM: # 135900), and the TUBA1A gene, causative of Lissencephaly 3 (MIM: # 611603), were recurrently mutated." (PMID 41153384, 2025).
mantle cell lymphoma (1 paper, 2023). Mantle cell lymphoma is a rare form of malignant non-Hodgkin lymphoma affecting B lymphocytes in the lymph nodes in a region called the ``mantle zone''. "In mantle cell lymphoma (MCL), recurrent mutations have been observed in SMARCA4 (mutation frequency ~ 6-10%), ARID2, ARID1A, and ARID1B (mutation frequency ~ 3-6% each)." (PMID 36810086, 2023).
marginal zone lymphoma (1 paper, 2023). A usually indolent mature B-cell lymphoma, arising from the marginal zone of lymphoid tissues. "In marginal zone lymphoma (MZL), recurrent mutations have been reported in ARID1A (7%) and ARID1B (4%)." (PMID 36810086, 2023).
memory impairment (1 paper, 2020). "Together, these results suggest that SST-specific Arid1b haploinsufficiency leads to several learning and memory impairments." (PMID 32398858, 2020).
myelodysplastic syndrome (1 paper, 2023). A clonal hematopoietic disorder characterized by dysplasia and ineffective hematopoiesis in one or more of the hematopoietic cell lines. "Moreover, sequencing studies carried out on AML and/or myelodysplastic syndromes (MDS) have found recurrent deleterious mutations in SWI/SNF genes including ARID2, ARID1A and ARID1B, SMARCA2, and SMARCA4." (PMID 36941700, 2023).
neuroma (1 paper, 2022). A tumor that grows from a nerve or is composed of nerve cells and nerve fibers. "Using the provided data as reference enabled us to objectively diagnose CN abnormalities, such as abnormal formation of CN3 (Col4a2), neuroma of the motor portion of CN5 (Arid1b), thinning of CN7 (Rpgrip1l) and abnormal topology of CN12 (Cc2d2a)." (PMID 36438572, 2022).
Noonan syndrome (1 paper, 2018). Noonan Syndrome (NS) is characterized by short stature, typical facial dysmorphism and congenital heart defects. "Four patients who carried LGD variants in known DD genes (POGZ, ARID1B, FOXP1, and SIN3A) and one patient who carried a known activating variant in the Noonan syndrome gene PTPN11 were considered pathogenic variants by the American College of Medical Genetics and Genomics guidelines." (PMID 30532227, 2018).
osteoarthritis (1 paper, 2019). A noninflammatory degenerative joint disease occurring chiefly in older persons, characterized by degeneration of the articular cartilage, hypertrophy of bone at the margins and changes in the synovial membrane. "Osteoarthritis mapped to a long intergenic region on chromosome 1, between genes encoding for NADPH oxidase 3 (NOX3), an intriguing candidate for articular cartilage degradation, and AT-rich interactive domain 1B (ARID1B) that has been previously linked to joint laxity." (PMID 31881848, 2019).
osteosarcoma (1 paper, 2021). A usually aggressive malignant bone-forming mesenchymal neoplasm, predominantly affecting adolescents and young adults. "Furthermore, ARID1B interacts with β-catenin in a human osteosarcoma cell line, and the ARID1B-β-catenin interaction in these cells is mediated by BRG137." (PMID 33594090, 2021).
Pierpont syndrome (1 paper, 2014). "In addition, we carried out mutation analysis of ARID1B (but not other members of the BAF complex) in four patients with classical features of Pierpont syndrome including patient 1 of the original case report and did not identify any mutation (unpublished data)." (PMID 24674232, 2014).
pilocytic astrocytoma (1 paper, 2018). Pilocytic astrocytoma is a rare subtype of low-grade glioma of the central nervous system characterized by a well circumscribed, often cystic, brain tumor with a discrete mural nodule and long, hair-like projections that extend from the neoplastic astrocytes. "Histologic examination showed pilocytic astrocytoma (PA) with anaplasia, and molecular characterization revealed FGFR1 duplication with additional variants of unknown significance in several genes (ARID1A, ARID1B, CHEK2, EPHA5, and MLL2)." (PMID 29610389, 2018).
subungual melanoma (1 paper, 2022). "Also, it has been reported that subungual melanoma harbors more distinct genomic alterations including CARD11, ARID2, ARID1A, ARID1B, PTPRB, and PTPRK genes, compared with acral melanoma." (PMID 35484605, 2022).
synovial sarcoma (1 paper, 2025). "Disruption of Arid1a or Arid1b (both CBAF-specific) retains synovial sarcoma character, while Smarcb1 (PBAF- and CBAF-specific) or Pbrm1 (PBAF-specific) disruption does not, although all accelerate SS18::SSX-driven tumorigenesis in mice." (PMID 41423472, 2025).
tuberous sclerosis complex (1 paper, 2019). "A young woman with NDD due to a de novo mutation in ARID1B now presented with a large renal (> 19 cm in diameter) and multiple hepatic angiomyolipomas (AMLs) but no other signs of tuberous sclerosis complex." (PMID 31077186, 2019).
undifferentiated carcinoma (1 paper, 2023). A usually aggressive malignant epithelial neoplasm composed of atypical cells which do not display evidence of glandular, squamous, or transitional cell differentiation. "So far, there have not been noticeable clinical or morphologic differences associated with ARID1B that differentiate it from the other two core subunits in DDC/UDC, and all are currently classified under the same umbrella terminology of dedifferentiated or undifferentiated carcinomas." (PMID 37686505, 2023).
uveal melanoma (1 paper, 2022). A melanoma derived from melanocytes of the uveal tract. "Thus, in cutaneous, mucosal, and uveal melanomas, there is a strikingly high frequency of mutations in ARID1B." (PMID 35323214, 2022). "Interestingly, both cutaneous and uveal melanomas are among the cancers with the most frequent ARID1B genetic alterations." (PMID 35323214, 2022).
viral infection (1 paper, 2024). "We found that ARID1B-deficient cells exhibited activation of the cGAS-STING signaling pathway 31-39, which is involved in the innate immune response to DNA damage and viral infection." (PMID 38577613, 2024).
cancer (114 papers, 2014 to 2026). A tumor composed of atypical neoplastic, often pleomorphic cells that invade other tissues. "Loss of ARID1B is synthetically lethal in ARID1A-deficient cancer cells, suggesting that ARID1B is a therapeutic target in ARID1A-deficient cancers." (PMID 41017120, 2025). "ARID1B mutations, including protein loss resulting from nonsense, frameshift, and insertion/deletion mutations, are prevalent in human diseases and cancers." (PMID 38577613, 2024). "In ARID1A mutant tumor cells, the loss of ARID1B leads to the loss of enhancer structure and changes in chromatin accessibility, making it challenging for cancer cells to survive." (PMID 38008753, 2023). "In recent years, ARID1A and ARID1B co-mutations have been found in various cancers, but at least one functional allele has survived." (PMID 38008753, 2023). "In ARID1A-deficient cancers, at least one functional ARID1B allele is maintained, and loss of ARID1B leads to destabilization of the SWI/SNF complex and subsequent impaired cell proliferation." (PMID 36980292, 2023). "ARID1B is essential for the survival of ARID1A mutated cancer cells, by supplying residual BAF complex activities to maintain chromatin accessibility at enhancers and regulate RNA polymerase II dynamics." (PMID 35715442, 2022). "Since the cBAF complex requires either ARID1A or ARID1B, the inactivation of ARID1B has been viewed as a potential vulnerability for ARID1A-mutated cancers." (PMID 36605718, 2022). "Loss-of-function ARID1A-mutant cancers are sensitive to ARID1B KO, causing destabilization of the SWI/SNF chromatin remodeling complex." (PMID 36040810, 2022). "Defects in the chromatin remodelling factor, ARID1B, cause extensive dysregulation across different cancer types." (PMID 36313455, 2022). "In ARID1A mutated cancers, the co-mutation of ARID1B destabilizes the SWI/SNF complex and damages cell proliferation, suggesting a potential target for malignancies harboring ARID1A mutations." (PMID 35303910, 2022). "While haploinsufficiency of ARID1A can drive cancer formation, upon its loss, the paralogous subunit, ARID1B, promotes cBAF binding to pro-tumorigenic loci." (PMID 35323214, 2022). "Recently, ARID1A, a paralog of ARID1B, whose deficiency is implicated in the promotion of cancer progression, was identified as being able to induce senescence and the progression of pancreatic intraepithelial neoplasia (PanIN)." (PMID 36361605, 2022). "SWI/SNF-deficient dedifferentiated and undifferentiated carcinomas can be confirmed by the loss of ARID1B, BRG1 or INI1 by IHC." (PMID 35053578, 2022). "In some cases, synthetic lethality is caused by the concomitant knockout of two mutually exclusive paralogues: Tumours with a SMARCA4 deficiency are sensitive to SMARCA2 depletion, and ARID1B is required for survival of ARID1A-mutant cancers." (PMID 33941852, 2021). "Among the non-synonymous mutations, 33 were present in both cell line and primary tumor, including truncating mutations of ARID1A and ARID1B genes and a cancer hotspot missense mutation of DICER1 gene (p.D1810Y)." (PMID 33052929, 2020). "ARID1A or ARID1B mutations and the resultant functional deficiencies are tightly associated with cancer mutability, PD-L1 expression and TIME modulation and are associated with a good prognosis for ICIs treatment." (PMID 32791957, 2020). "The bioinformatic analyses in this research indicated that ARID1A or ARID1B mutations were associated with instability in the cancer cell genome and cancer mutability, as indicated by the elevated TMB, which is a proven biomarker for cancer immunotherapy." (PMID 32791957, 2020). "This opens the opportunity to evaluate the biological function of SWI/SNF mutations, particularly ARID1B loss, in cancer development." (PMID 33052929, 2020). "ARID1B therefore belongs to a growing number of genes in which germline mutations cause NDDs while somatic mutations are involved in cancer." (PMID 31077186, 2019).